CTRL (chymotrypsin like)
Synonyms: CTRL1
Tractability: Small molecule: a high-quality ligand is known. Antibody: UniProt predicts a signal peptide or a membrane-spanning region. PROTAC: a small molecule that binds it is known.
Target class: Serine protease; Enzyme; Serine protease PA clan; Serine protease S1A subfamily; Protease
Gene: Protein-coding gene on chromosome 16 (67,927,640 to 67,932,365, reverse strand). Ensembl gene ENSG00000141086.
Pathways (Reactome):
Developmental Biology: Developmental Lineage of Pancreatic Acinar Cells
Gene Ontology:
Molecular function: protein binding; serine-type peptidase activity; serine-type endopeptidase activity; peptidase activity
Biological process: protein catabolic process; proteolysis
Cellular component: extracellular region
Genetic constraint (gnomAD): Loss-of-function variants: 38 observed, 36.31 expected, observed/expected ratio (o/e) 1.05, 90% interval 0.81 to 1.37. The upper end of that interval is the gene's LOEUF score, 1.37, which puts it in group 5 of 6, group 1 being the genes least tolerant of losing a copy. Missense variants: 327 observed, 353.85 expected, observed/expected ratio (o/e) 0.92, 90% interval 0.84 to 1.01. Synonymous variants: 155 observed, 144.13 expected, observed/expected ratio (o/e) 1.08, 90% interval 0.94 to 1.23.
Homologues: Orthologues: chimpanzee CTRL (98% identical), pig CTRL (89% identical), mouse Ctrl (86% identical), dog CTRL (85% identical), rat Psmb10 (72% identical), rabbit CTRL (66% identical), zebrafish ctrl (62% identical), zebrafish zgc:171592 (56% identical), zebrafish si:dkey-238d18.3 (51% identical). Paralogues in human: PRSS38 (38% identical).